MIIP (migration and invasion inhibitory protein)
Description:
Inhibits glioma cells invasion and down-regulates adhesion- and motility-associated genes such as NFKB2 and ICAM1. Exhibits opposing effects to IGFBP2 on cell invasion.
Synonyms: IIp45; FLJ12438
Tractability: PROTAC: ubiquitination databases record sites on it.
Gene: Protein-coding gene on chromosome 1 (12,019,466 to 12,032,046, forward strand). Ensembl gene ENSG00000116691.
Subcellular location (Human Protein Atlas): Nucleoplasm; Cytosol
Gene Ontology:
Molecular function: protein binding
Biological process: negative regulation of cell migration; negative regulation of G2/M transition of mitotic cell cycle
Genetic constraint (gnomAD): Loss-of-function variants: 44 observed, 45.48 expected, observed/expected ratio (o/e) 0.97, 90% interval 0.76 to 1.24. The upper end of that interval is the gene's LOEUF score, 1.24, which puts it in group 5 of 6, group 1 being the genes least tolerant of losing a copy. Missense variants: 496 observed, 524 expected, observed/expected ratio (o/e) 0.95, 90% interval 0.88 to 1.02. Synonymous variants: 225 observed, 223.02 expected, observed/expected ratio (o/e) 1.01, 90% interval 0.9 to 1.13.
Homologues: Orthologues: chimpanzee MIIP (97% identical), macaque MIIP (79% identical), pig MIIP (64% identical), guinea pig MIIP (59% identical), mouse Miip (56% identical), rat Miip (54% identical), tropical clawed frog miip (30% identical), zebrafish miip (27% identical).
Diseases named in the same sentence as MIIP in open-access papers:
MIIP is named in the same sentence as 30 diseases in open-access papers, as found by Europe PMC text mining. Sharing a sentence is not in itself a finding about the gene and the disease. The quoted sentences say what the papers report.
glioma (12 papers, 2008 to 2024). A benign or malignant brain and spinal cord tumor that arises from glial cells (astrocytes, oligodendrocytes, ependymal cells). "The migration and invasion inhibitory protein, which is encoded by the recently discovered MIIP (also termed IIp45) gene, located on chromosome 1p36.22 and spanning 12.6 kb of genomic DNA, inhibits migration and invasion of human glioma cells." (PMID 27760566, 2016). "Thus, loss of MIIP promotes cell cycle progression and mitotic activity during development and progression of gliomas." (PMID 22817864, 2012). "MIIP was characterized by its role in inhibiting migration and invasion in glioma, and hence the name." (PMID 36130933, 2022). "FOXO1 binds and transcriptionally activates Phosphotyrosine Interaction Domain Containing 1 (PID1) and Migration and Invasion Inhibitory Protein (MIIP), that induce apoptosis and inhibit glioma growth and invasion." (PMID 31450858, 2019). "The expression level of MIIP is decreased in many types of cancer, including glioma, lung cancer, colon cancer, endometrial carcinoma and pancreatic cancer, and correlates with advanced clinical stage and shorter survival time of the patients." (PMID 31092266, 2019). "In the GAS5/miR-196a-5p/FOXO1/PID1 (MIIP) pathway of glioma stem cells, FOXO1 promotes GAS5 transcription and forms a positive feedback loop that regulates the biological behavior of glioma stem cells." (PMID 30736838, 2019). "MIIP can inhibit the formation and invasion of glioma cells, induce mitotic catastrophe, and inhibit cell migration and invasion in breast cancer." (PMID 30043279, 2018). "We found that MIIP expression is deceased in EC tissues, especially in patients with deep myometrial invasion, advanced stage, and lymph node metastasis which is consistent with a previous study reporting decreased MIIP in advanced gliomas." (PMID 27760566, 2016). "The MIIP protein has been previously observed to inhibit glioma cell migration and invasion in vitro and in vivo, and a xenograft model study revealed that tumors formed from MIIP-expressing cells were also less invasive as compared with the controls." (PMID 25360165, 2014). "The migration and invasion inhibitor protein (MIIP), also known as invasion inhibitory protein 45 (IIp45), is a recently characterized putative tumor suppressor gene in glioma." (PMID 25360165, 2014). "Studies have revealed that MIIP expression levels were reduced in glioblastoma multiforme and that IIp45 expression levels were low in advanced glioma." (PMID 25360165, 2014). "The migration and invasion inhibitor protein (MIIP, also known as IIp45) was discovered as a negative regulator of cell migration and invasion in glioma and its expression was reduced or undetectable in tissue samples obtained from patients with GBM." (PMID 22817864, 2012). "Emerging studies indicate that MIIP is downregulated in a variety of human tumors, including prostate cancer, glioma, lung cancer, colon cancer, endometrial carcinoma, and pancreatic cancer; moreover, its expression level is correlated with advanced clinical stage and patient prognosis." (PMID 34931765, 2021). "This supports our hypothesis that the MIIP gene functions as a migration inhibitor in EC cells, similar to what has been observed in glioma cells." (PMID 27760566, 2016). "Migration and invasion inhibitory protein [MIIP, also known as IIp45] was initially identified as a binding partner of insulin-like growth factor-binding protein 2 (IGFBP2) and a negative regulator of cell invasion in glioma." (PMID 38245780, 2024). "MIIP is able to interact with Cdc20 and suppress the activity of APC/CCdc20, thus blocking the degradation of two mitotic check proteins, cyclin B1 and securing, leading to impaired mitotic transition in glioma and colon cancer model." (PMID 31092266, 2019).
glioma (continued). "Of the two Type 1 hits, MIIP (migration and invasion inhibitory protein) was initially identified in a yeast-two-hybrid screen as a binding partner for the insulin-like growth factor binding protein 2 (IGFBP2) and shown to inhibit glioma cell invasion." (PMID 26466362, 2015).
pancreatic cancer (7 papers, 2019 to 2025). "Additionally, poorly regulated miRNAs have the potential to cause pancreatic cancer, the dysregulated miR-646 and MIIP expression being associated with the exacerbation of pancreatic cancer." (PMID 34836055, 2021). "Migration and invasion inhibitory protein (MIIP) is identified as oncogenic blocker in pancreatic cancer." (PMID 33109235, 2020). "Interestingly, a recent study on pancreatic cancer has reported that MIIP leads to destabilization of HIF-1α by inhibiting the deacetylase activity of HDAC6 and thereby enhancing HIF-1α acetylation." (PMID 34931765, 2021). "Migration and Invasion Inhibitory Protein (MIIP) has recently been identified as an inhibitor of tumor development and constitutes a negative feedback loop with HIF1α in pancreatic cancer." (PMID 35651786, 2022). "Recently, it was shown that migration and invasion inhibitory protein (MIIP) inhibits the growth of tumors and forms a negative feedback loop with HIF1a in pancreatic cancer." (PMID 40227591, 2025).
prostate carcinoma (6 papers, 2019 to 2024). A carcinoma that arises from epithelial cells of the prostate gland. "Previous research findings have indicated the downregulation of MIIP in a range of malignancies, encompassing endometrial cancer, ovarian cancer, breast cancer, prostate cancer, non-small cell lung cancer, glioma, and colon cancer." (PMID 38372808, 2024). "Previous studies focusing on urinary system tumors revealed that MIIP directly interacts with PP1α, negatively regulating the Akt pathway, and inhibiting prostate cancer proliferation." (PMID 38245780, 2024). "In a recent study, it was found that the PI3K/AKT signaling pathway can be regulated by MIIP to inhibit the progression of prostate cancer." (PMID 38372808, 2024). "The MIIP-miR-181a/b-5p-KLF17 axis has been shown to inhibit prostate cancer epithelial-mesenchymal transition (EMT)." (PMID 38245780, 2024). "MIIP has been identified as downregulated in various types of tumors, and its functional roles and clinical significance have been demonstrated in prostate cancer and clear cell renal cell carcinoma in our previous studies." (PMID 38245780, 2024). "Here we for the first time demonstrated that MIIP inhibits prostate cancer cell proliferation by interacting with PP1α and facilitating PP1α-dependent dephosphorylation of AKT and attenuation of downstream AKT-mTOR signaling pathway." (PMID 31092266, 2019). "We showed here that overexpression of MIIP inhibit prostate cancer cell growth both in vitro and in nude mice." (PMID 31092266, 2019). "In summary, we for the first time demonstrated here that MIIP is a novel suppressor of prostate cancer and the higher the Gleason score, the lower its expression." (PMID 31092266, 2019). "In addition, our recent studies have demonstrated that MIIP is downregulated in prostate cancer, and its overexpression inhibits tumor growth and epithelial-mesenchymal transition by modulating PP1α-AKT signaling and the miR-181a/b-5p-KLF17 axis, respectively." (PMID 34931765, 2021). "Moreover, migration and invasion inhibitory protein (MIIP) inhibits cell invasion and epithelial–mesenchymal transition in prostate cancer through miR-181a/b-5p-KLF17 axis." (PMID 33648424, 2021). "Here, we show that forced expression of MIIP inhibits the growth of both AR- positive and negative prostate cancer cell lines as well as the corresponding xenograft, while knockdown of MIIP does the opposite." (PMID 31092266, 2019).
colon cancer (4 papers, 2017 to 2021). "More interestingly, the most recent study reported that MIIP interacts with PP1 and serves as its substrate of dephosphorylation at S303, which undergoes phosphorylation by PKCε upon EGF-treatment in colon cancer." (PMID 31092266, 2019).
colorectal cancer (4 papers, 2017 to 2026). A primary or metastatic malignant neoplasm that affects the colon or rectum. "MIIP down-regulation in colorectal cancer cells led to an increase in AZGP1 N-glycosylation and subsequent aberrant secretion of AZGP1, which, in turn, induced peri-cancerous WAT browning and lipolysis via the cAMP–PKA pathway." (PMID 38245780, 2024). "For instance, positive correlation of MIIP high expression with poor prognosis was observed in esophageal squamous cell carcinomas; and phosphorylation of MIIP at Ser303 by PKCε could enhance RelA transcriptional activity and thus promote metastasis of colorectal cancer." (PMID 36130933, 2022). "Meanwhile, MIIP might also have tumor-promoting ability, evident by the findings that MIIP was highly expressed in the esophageal squamous cell carcinoma tissues compared to adjacent normal tissues; and phosphorylation of MIIP at Ser303 facilitated metastasis of colorectal cancer." (PMID 36130933, 2022). "In light of this, we conducted RNA-seq and RT-qPCR analyses to assess the potential impact of MIIP overexpression or knockdown on the expression of STT3A and STT3B in both human and mouse colorectal cancer (CRC) cell lines." (PMID 38245780, 2024).
endometrial carcinoma (4 papers, 2016 to 2021). A malignant tumor arising from the epithelium that lines the cavity of the uterine body. "MIIP may function as a tumor suppressor gene for endometrial carcinoma." (PMID 27760566, 2016).
lung carcinoma (4 papers, 2016 to 2021). "We observed that EGFR protein was decreased in lung cancer cells by MIIP overexpression and increased by MIIP knockdown." (PMID 26824318, 2016). "In our MIIP-overexpressing lung cancer cells, EGFR level decreased as early as the appearance of the semiglycosylated 160-kD EGFR peptides." (PMID 26824318, 2016). "The MIIP gene is located on chromosome 1p36.22, which is one of the most frequently deleted regions in a wide spectrum of human cancers, including lung cancers." (PMID 26824318, 2016). "MIIP inactivation was also reported in breast, esophageal, and lung cancer." (PMID 27760566, 2016). "As we had proven that MIIP decreases EGFR/Ras/MEK/ERK pathway activation via decrease of EGFR protein expression, we tested the growth of MIIP-overexpressing or knockdown lung cancer cells." (PMID 26824318, 2016). "After transfection with the MIIP plasmid, steady-state EGFR protein expression was downregulated to about 30% of that in control cells in the three lung cancer cell lines used." (PMID 26824318, 2016). "Therefore, MIIP accelerates degradation of both semiglycosylated and mature EGFR in H1299 lung cancer cells." (PMID 26824318, 2016). "In summary, we have found that tumor suppressor MIIP promotes EGFR degradation via both the proteasomal and lysosomal pathways, resulting in downregulation of EGFR downstream signaling and ultimately in inhibition of lung cancer cell growth." (PMID 26824318, 2016). "Furthermore, MIIP-promoted downregulation of EGFR inhibits downstream activation of Ras and blocks the MEK signal transduction pathway, resulting in inhibition of lung cancer cell proliferation." (PMID 26824318, 2016). "Thus, the results from clinical NSCLC samples were consistent with our finding from in vitro experiments that MIIP accelerated EGFR protein turnover and resulted in the inhibition of lung cancer cell proliferation." (PMID 26824318, 2016). "Interestingly, EGFR protein expression was not increased by MIIP shRNA in A549 cells, which had the highest endogenous EGFR levels among the lung cancer cell lines we tested." (PMID 26824318, 2016).
non-small cell lung carcinoma (3 papers, 2016 to 2024). A group of at least three distinct histological types of lung cancer, including non-small cell squamous cell carcinoma, adenocarcinoma, and large cell carcinoma. "Research has indicated that MIIP has the capability to expedite the degradation of EGFR while concurrently suppressing the downstream Ras/MEK/ERK signaling cascade, consequently curbing the proliferation and metastasis of non-small cell lung cancer." (PMID 38372808, 2024). "Moreover, MIIP can accelerate EGFR degradation and inhibit downstream Ras/MEK/ERK signal pathway, resulting in inhibition of cell proliferation of non-small cell lung cancer." (PMID 31092266, 2019).
breast carcinoma (2 papers, 2018 to 2022). "In breast cancer, the case-control study for the SNPs or LOH of MIIP, and the association between MIIP expression and clinical prognosis factors or cell biologic behaviors suggested the involvement of MIIP in breast cancer development and progression." (PMID 36130933, 2022). "When analyzing MIIP expression among different prediction analysis of microarray 50 (PAM50) subtype tumors, we found basal-like tumors had relatively higher expression of MIIP, implying the crucial role of MIIP in this subtype of breast cancer." (PMID 36130933, 2022). "To investigate the role of MIIP in breast cancer, we first analyzed the expression and copy number alteration of MIIP in breast cancer using public databases." (PMID 36130933, 2022). "The results from the survival analysis using TCGA database and immunohistochemistry staining of a breast cancer tissue array suggested that patients with high expression of MIIP had a better survival outcome." (PMID 36130933, 2022). "Expression of MIIP in breast cancer is lower than in normal tissues." (PMID 36130933, 2022). "Simultaneously, MIIP was negatively correlated with ITGB3 in expression in breast cancer." (PMID 36130933, 2022). "Additionally, MIIP shallow deletion is correlated with decreased MIIP mRNA expression, which occurs in majority of breast cancer samples." (PMID 36130933, 2022). "Interestingly, MIIP expression was higher in TNBC than in other subtypes of breast cancer." (PMID 36130933, 2022). "However, the exact role of MIIP in breast cancer or even in cancer is not well understood yet." (PMID 36130933, 2022). "Through analysis of the TCGA breast cancer database, we identified a negative correlation between MIIP mRNA levels and β-catenin protein levels in breast cancer samples." (PMID 36130933, 2022).
clear cell renal cell carcinoma (2 papers, 2021 to 2024). "Herein, we sought to explore the function of MIIP in clear cell renal cell carcinoma (ccRCC)." (PMID 34931765, 2021). "Additionally, MIIP promotes HIF-2α ubiquitination, inhibiting clear-cell renal cell carcinoma proliferation and angiogenesis." (PMID 38245780, 2024).
glioblastoma (2 papers, 2008 to 2014). The most malignant astrocytic tumor (WHO grade IV). "The results of real-time PCR and immunohistochemical staining clearly demonstrated that MIIP expression was downregulated in cancer tissues, as compared with matched normal tissues, a finding consistent with the results previously reported in a study analyzing glioblastoma multiforme." (PMID 25360165, 2014).
invasive breast carcinoma (2 papers, 2022). A carcinoma that infiltrates the breast parenchyma. "Among the different MIIP genomic alterations, gene deletion and mutation are the relatively frequent events in invasive breast cancer, and the MIIP gene locus has relatively high frequency of copy number loss." (PMID 36130933, 2022).
lymph node metastasis (2 papers, 2016 to 2020). "In the study presented here, we demonstrate that decreased expression of MIIP was significantly associated with deep myometrial invasion, advanced stage, and the presence of lymph node metastasis in EC." (PMID 27760566, 2016). "We demonstrate that MIIP expression was significantly decreased in EC patients comparing to the normal ones, and decreased MIIP expression in EC tissues is associated with deep myometrial invasion, advanced stage, and the presence of lymph node metastasis." (PMID 27760566, 2016). "Detailed clinical correlation analyses revealed that among the 205 EC patients, a low level of MIIP expression was associated with deep myometrial invasion, lymph node metastasis, and advanced FIGO stage." (PMID 27760566, 2016). "An evaluation of the MIIP levels in 205 EC patient samples, 63 with atypical hyperplasia and 116 with normal tissue, revealed that EC patients had elevated expression of MIIP associated with an advanced stage of the disease and lymph node metastasis." (PMID 32443784, 2020). "We found that MIIP expression is decreased in ECs, especially in deep myometrial invasion, or advanced stage cases and those with lymph node metastasis." (PMID 27760566, 2016).
melanoma (2 papers, 2008 to 2025). A malignant, usually aggressive tumor composed of atypical, neoplastic melanocytes. "Studies in melanoma reveal that low expression of MIIP and high expression of its downstream molecule HDAC6 correlate with poorer overall survival, with a positive correlation between HDAC6 and PD-L1 protein expression." (PMID 40573881, 2025). "Experimental evidence indicates that the HDAC6/STAT3 axis regulates PD-L1 expression, suggesting that targeting the MIIP/HDAC6/PD-L1 pathway might enhance immune checkpoint inhibitor efficacy in melanoma." (PMID 40573881, 2025).